FAP (fibroblast activation protein alpha)
Diseases named in the same sentence as FAP in open-access papers (continued):
Sharing a sentence is not in itself a finding about the gene and the disease.
tumor (continued). "Animal assay suggests that tumor burden has been enhanced by FAP significantly in vivo." (PMID 30419872, 2018). "Indeed, it has been shown, in a murine model, that FAP+ tumor cells can be used as a vaccine, leading to reduced vascular dissemination and elimination of different tumors." (PMID 29515580, 2018). "A subpopulation of F4/80hi TAMs was identified in subcutaneous murine Lewis lung adenocarcinoma (LL2) tumours, which expressed surface fibroblast activation protein alpha (FAP) and intracellular haem oxygenase-1 (HO-1) and accounted for 10% of total F4/80hi cells." (PMID 30054470, 2018). "The tumor volume and weight in the NC group were significantly lower than FAP group." (PMID 30419872, 2018). "Additionally, high expression is detected in the tumor microenvironment, but FAP is rarely detectable in normal tissues." (PMID 30038550, 2018). "The catalytic activity of FAP was shown to be necessary for tumor proliferation." (PMID 30103384, 2018). "In addition, this finding supports the concept that FAP is an important molecular target to inhibit tumor invasion and metastasis." (PMID 29938002, 2018). "The anti-tumor activity of FAP inhibition was enhanced upon addition of anti-PD-1 therapy." (PMID 30400822, 2018). "In addition, FAP can be also expressed by tumor cells; this would imply that an immune-based therapy focused on FAP can beat both tumor cells and TAF." (PMID 29515580, 2018). "Chen and colleagues developed a prodrug, namely, Z-GP-DAVLBH, which can be selectively activated by fibroblast activation protein α (FAPα) in TP, destroying the cytoskeleton of FAPα-expressing TP, promoting blood vessels disruption, and turning the tumour more responsive to VDA treatments." (PMID 30406137, 2018). "Whereas, tumour associated immune cells (TAMS), tumour associated fibroblasts (e.g., FAP, α-SMA, FGFRs, tenascin-C and thrombospondin-1) and tumour initiating stem cells (e.g., CD133, EpCAM and aldehyde dehydrogenases), have been utilised to allow for NPPSs drug targeting within a TME." (PMID 30322132, 2018). "Taken together, we described the tumor promoting functions of stromal FAP, which might account for GC progression." (PMID 30419872, 2018). "Expression of tumoural Hmox1, the gene encoding HO-1, was also detected at the point of tumour establishment (day 9 post inoculation) and was associated with the TAM population, where its expression correlated with FAP." (PMID 30054470, 2018). "In this regard, the IHC detection of FAP in the stromal tumor fibroblasts could be a potential biomarker of early lymph node metastatic status and therefore could account for the poor prognosis of FAP positive CCRCC." (PMID 30518081, 2018). "We propose that the assay presented here could guide preclinical investigations of FAP biology and the clinical development of FAP inhibitors or FAP-localized anti-tumor therapies in the future." (PMID 28970566, 2017). "FAPα is a member of serine protease family possessing gelatinase activity and type I collagenase activity, which is a vital type II transmembrane protein expressed in more than 90% epithelial tumor stromal cells." (PMID 28881756, 2017). "Hence, FAP-α is known to give shape to the microenvironment which promotes growth as well as invasion of the tumor by degrading ECM." (PMID 28492519, 2017). "Circulating FAPα is previously speculated to derive from two distinct sources in cancer patients: yet-to-be-identified physiologic source(s), and the tumor." (PMID 28415791, 2017). "Results suggested fibroblast activation protein alpha and epithelial cell adhesion molecule circulating tumor cells are distinct subpopulations and the use of these in concert can provide information needed to navigate through cancer disease management challenges." (PMID 29657983, 2017).
tumor (continued). "Mild to moderate FAP staining could be clearly detected in the tumour stroma and was significantly stronger than in the normal stroma, where only negligible staining could be detected, except for vessel walls." (PMID 28531107, 2017). "In addition, FAP is expressed in some tumour cells and in a minor population of intratumoural CD45+F4/80hiCCR2+CD206+ M2 macrophages." (PMID 28158223, 2017). "To determine whether extratumoral H2O2 transforms normal FIBs into a CAF-like phenotype in vivo, we examined intracellular ROS levels and FAP expression in VybrantDiO-labeled FIBs isolated from tumor xenografts by FACS analysis." (PMID 28102840, 2017). "Hence, the tumor growth was controlled by depleting FAP+ cells in an adaptive immunity-dependent manner, thereby concluding that tumor microenvironment stromal cells exert a suppressive effect on anti-tumor immunity." (PMID 28881756, 2017). "FAPα, as a member of the dipeptidyl prolyl peptidase (DPP) family, has been reported to be a competent diagnostic and therapeutic target because of its high expression in solid tumors and its potential function in tumor invasion." (PMID 28415791, 2017). "There is still no consistent conclusion as to why the drug did not work, but there are reports suggesting that the enzymatic activity of FAP α has little to do with increased tumor growth, and there are also contradictory results suggesting that serine proteases can function as tumor suppressors." (PMID 26985769, 2016). "Overall our data suggest that depleting FAP+ tumor stromal cells can decrease the metabolic stress of MAA-specific CD8+ TILs, which delay their differentiation towards functional exhaustion within the TME and result in significantly improved antitumor efficacy." (PMID 26943036, 2016). "Furthermore, evidence for the detection of FAP-expressing tumor cells and cells of the tumor stroma by activatable FAP-targeting liposomes is presented in this dataset." (PMID 27642620, 2016). "Mice with a genetic deletion of the FAP gene show prolonged survival after tumor challenge." (PMID 26943036, 2016). "Also, primary and metastatic FAP expression was correlated with large tumor diameter (>7cm), high grade (G3/4), high stage (pT3/4), tumor necrosis and sarcomatoid transformation." (PMID 28033421, 2016). "We assume that this may reflect that FAP+ cells become more frequent during tumor growth so that a vaccine that delays tumor progression also reduces accumulation of FAP+ cells." (PMID 26943036, 2016). "Indeed our data show that most of the factor-producing transcripts that changed upon FAP vaccination originated from tumor infiltrating leukocytes and CD14+ cells." (PMID 26943036, 2016). "FAP α+/CD45+ cells are the major tumoral source of HO-1, and an inhibitor of HO-1, Sn-mesoporphyrin, causes the same extent of immune-dependent arrest of LL2/OVA tumor growth as does the depletion of these cells." (PMID 26985769, 2016). "Factors secreted by FAP+ stromal cells may also interfere with T cell-tumor cell interactions and hinder tumor cell lysis." (PMID 26943036, 2016). "To achieve immune-mediated destruction of the tumor stroma, we developed a vaccine based on a replication-defective Ad vector of chimpanzee serotype 68 (AdC68), which expresses full-length murine FAP protein from a CMV-promoter driven transgene incorporated into the vector's deleted E1 domain." (PMID 26943036, 2016). "Most of the FAP+ cells within either tumor only expressed low to intermediate levels of CD45." (PMID 26943036, 2016). "As a proxy for the quantity of original patient stroma in each PDX sample, human expression levels of two CAF markers that are rarely expressed by tumor epithelial cells, fibroblast activation protein alpha (FAP) and chondroitin sulfate proteoglycan 4 (CSPG4), were assessed." (PMID 26980748, 2016).
tumor (continued). "To determine the mechanism by which the AdC68-mFAP vaccine delayed tumor progression, we first analyzed whether AdC68-mFAP vaccine-induced immune responses could destroy FAP+ stroma cells." (PMID 26943036, 2016). "As remains to be investigated in more depth, it is feasible that depletion of FAP+ cells and reductions in ISCs affect metabolic pathways used by tumor cells and other cells within the TME and thereby increases the amount of glucose that is available to CD8+T cells." (PMID 26943036, 2016). "The high correlation between the six extracellular matrix-associated lncRNAs with CAF markers FAP and ACTA2 may suggest a role for lncRNAs in the acquisition of an activated phenotype by fibroblasts in the tumour stroma." (PMID 27685983, 2016). "Immunohistochemical detection of FAP in the stromal tumor fibroblasts could be a biomarker of early lymph node metastatic status and therefore could account for the poor prognosis of FAP positive CCRCC." (PMID 28033421, 2016). "Furthermore, FAP is expressed on several tumor cells and thus it is difficult to define the relative contribution of MSC and neoplastic cells to TME due to this enzyme." (PMID 27834810, 2016). "Besides antibodies FAP vaccination studies have resulted in some excitement in preclinical level demonstrating significantly reduced tumor growth and metastasis in B16/F10.9 melanoma, 4T1 breast cancer, and EL4 thymoma mouse models." (PMID 26798356, 2016). "Furthermore, co-inhibitor PD-1 levels were also significantly lower on MAA-specific CD8+TILs upon FAP+ cell depletion in both tumor models, suggesting that these cells were partially protected from exhaustion." (PMID 26943036, 2016). "Decreases in ISCs upon FAP+stromal cell depletion is associated with reduced metabolic stress of vaccine-induced tumor infiltrating CD8+T cells and their delayed progression towards functional exhaustion, resulting in prolonged survival of tumor-bearing mice." (PMID 26943036, 2016). "Indeed, tumor cells expressing FAP can be used as a vaccine, leading to elimination of solid tumors and their vascular dissemination." (PMID 27834810, 2016). "Thus, an important implication of our findings is the possibility that increased FAP expression by TAFs in the tumor stroma results in the cleavage of type I collagen to promote the localized accumulation of macrophages." (PMID 26934296, 2016). "A monoclonal antibody named F19 was produced to define the FAP α-positive cell, which strongly labeled cultured fibroblasts, fibroblasts in fetal mesenchymal tissues, the reactive stromal fibroblasts of epithelial tumors, and tumor cells of sarcomas." (PMID 26985769, 2016). "Tumor growth was comparable in the two groups that received single vectors (p=0.31), but was further retarded when the vaccines were combined (gDMelapoly+Co vs. gDMelapoly+FAP: p=0.0096)." (PMID 26943036, 2016). "Treatment with PSB1115 led to a reduction in FAP positive cells within tumor tissue." (PMID 27590504, 2016). "While numerous markers, such as PDGFRα, periostin and fibroblast activation protein (FAP) have been reported to identify CAF within the tumor microenvironment, SMA is most commonly used to identify those CAF with an ‘activated’ tumor-promoting myofibroblastic phenotype." (PMID 27992856, 2016). "This analysis suggests that FAP may be a promising therapeutic approach for developing strategies against this protein, not only aiming at its interstitial expression in the tumor microenvironment but also in tumor cells." (PMID 25775399, 2015). "The abrogation of the enzymatic activity of FAP attenuates tumor growth." (PMID 26394925, 2015). "Antibodies that neutralized FAPα attenuated the tumor growth rate." (PMID 25593080, 2015). "Fibroblast activation protein (FAP) plays a vital role in tumor invasion and metastasis." (PMID 25775399, 2015).
tumor (continued). "Notably, the FAP-expressing tumor cells directly targeted both tumor cells and CAFs in tumors and reversed the immunosuppressive effects of tumors by reducing the recruitment of immunosuppressive cells and enhancing the recruitment of effector T cells." (PMID 26394925, 2015). "FAP is also a key regulator during tumor growth and metastasis." (PMID 26300881, 2015). "These enzymatic activities indicate that FAPα may have a prominent role in tumor invasion, metastasis and angiogenesis." (PMID 25593080, 2015). "A study demonstrated that depleting FAPα-expressing cells in a transgenic mouse elicited antitumor immunity, and thus indicated that FAPα-expressing cells are an immune-suppressive component of the tumor microenvironment." (PMID 25593080, 2015). "We then performed immunohistochemical studies to determine whether IDO and FAPα were, in fact, expressed by the tumor tissues." (PMID 26305550, 2015). "FAPα expression may be elevated under the influence of an altered tumor microenvironment or inflammation." (PMID 25593080, 2015). "Tumor sections from vaccinated mice were stained with anti-FAP antibodies." (PMID 26394925, 2015). "However, further studies are required to determine the molecular mechanisms by which FAP-modified tumor cell vaccines are involved in the crosstalk between CAFs, tumor cells and infiltrating immune cells." (PMID 26394925, 2015). "However, recent studies targeting FAP using a novel FAP-activated prodrug that alters the activation of a cytotoxic compound in the tumor stroma have reported promising results." (PMID 25775399, 2015). "FAPα activity, alongside that of gelatinase and type I collagenase, has become increasingly important in cancer therapy due to its effectiveness in modulating tumor behavior." (PMID 25593080, 2015). "Tumor cells were transfected with murine FAP plasmids bearing the cationic lipid DOTAP." (PMID 26394925, 2015). "FAP expression is associated with worse prognosis in solid tumors, and this association is particularly pronounced if FAP overexpression is found in the tumor cells rather than the stroma." (PMID 25775399, 2015). "Indeed, in the present study we found that the number of FAP-positive cells was reduced by anti-OPN mAbs in primary tumor tissues, indicating that recruitment of CAFs are regulated via host-derived OPN." (PMID 26597716, 2015). "The relationship between FAP and poor prognosis may be stronger in those patients with FAP overexpression in tumor cells relative to patients with FAP overexpression in stroma”." (PMID 25775399, 2015). "Moreover, this study performed innovative subgroup analyses in patients with FAP overexpression in tumor cells or with different types of cancers, and the expected results were obtained." (PMID 25775399, 2015). "FAPα not only has an important role in regulating tumor behavior, but also influences CAF behavior." (PMID 25593080, 2015). "Taken together, these findings suggest that immunotherapy using an FAP-expressing vaccine induces immunity to both TAAs and FAP and stimulates the formation tumor-specific CTLs, predominantly CD8+ cells, which are directed toward antigens associated with the patient’s cancer." (PMID 26394925, 2015). "Therefore, the effect of FAP overexpression on tumor stroma or tumor cells or on different types of tumors requires further assessment." (PMID 25775399, 2015). "Our results indicated that the FAP-modified whole-cell tumor vaccine induced strong antitumor immunity against both tumor cells and CAFs and reversed the immunosuppressive effects of tumors by decreasing the recruitment of immunosuppressive cells and enhancing the recruitment of effector T cells." (PMID 26394925, 2015). "In fact, stimulation of HPFs with the medium of castration-resistant PCa cells was sufficient to increase α-SMA and FAP expression and to promote the acquisition of tumor-promoting properties, a phenotype abrogated by the administration of an anti-IL6 antibody." (PMID 26375444, 2015).
tumor (continued). "The 88-kDa murine FAP was detected in the pFAP-transfected tumor cells." (PMID 26394925, 2015). "Taken together, these studies indicated that FAPα is a tumor promoter." (PMID 25593080, 2015). "The IHC method was used to detect FAP expression in the tumor tissues of patients." (PMID 25775399, 2015). "By contrast, other studies have suggested that FAP has tumor-suppressive activity." (PMID 24520291, 2014). "Over-expression of FAP-α in fibroblasts and paracytes of cancer cells promotes tumour growth, invasion and metastasis by directly remodelling extracellular matrix and targeting fibroblast activation protein could inhibit tumour stromagenesis and growth." (PMID 24885257, 2014). "In contrast, it has also been shown that FAP-α can also act as a tumour promoter." (PMID 24885257, 2014). "Again, there are also contradictive results regarding the function of FAP-α in that it could act as both a tumour suppressor and tumour promoter." (PMID 24885257, 2014). "There is a clear discrepancy between FAP function in tumor promotion and suppression." (PMID 24520291, 2014). "A DNA vaccine directed against FAP-α could significantly suppressed primary tumour and pulmonary metastases through CD8+ T-cell-mediated killing in tumour-bearing mice." (PMID 24885257, 2014). "Recently, FAP showed immunosuppressive functions in a tumor microenvironment." (PMID 24551161, 2014). "FAP is considered to promote tumor cell growth and proliferation." (PMID 24520291, 2014). "In conclusion, the expressions of CCN2, EMA, and FAP may be involved in the formation of tumor fibrous stroma, along with activation of CAFs in HCC, giving rise to aggressive behavior." (PMID 25126747, 2014). "Additionally, EMA expression was associated with the expression of K19, CCN2, and FAP (P<0.05 for all); EMA expressing tumor epithelial cells showed a topographic closeness to FAP-expressing CAFs." (PMID 25126747, 2014). "There are also contradictive results about the function of FAP-α, in that it could act as both a tumour suppressor and tumour promoter." (PMID 24885257, 2014). "Finally, two groups took different approaches to ablate fibroblast activation protein-alpha (FAP+) stromal cells from the tumor microenvironment." (PMID 25099622, 2014). "Our hypothesis is that as a membrane protein, FAP-α might participate in the regulation of other membrane molecules or signaling pathways by which exert its influence on tumour cells." (PMID 24885257, 2014). "FAP is selectively expressed on fibroblasts within the tumor stroma or on CAFs." (PMID 25380303, 2014). "Interestingly, in HCCs with large tumor nests, EMA expression was higher at the peripheral portions of the tumor nests where tumor cells were more closely in contact with FAP-expressing CAFs." (PMID 25126747, 2014). "Taken together, we discerned that EMA and FAP may be important in tumor-stroma cross-talk via activation of CAFs." (PMID 25126747, 2014). "However, ablation of a subpopulation of stromal cells (FAP+ cells) permitted immune control of tumor growth and uncovered the efficacy of immunotherapeutic antibodies (anti-CTLA-4 or anti-PD-L1), which resulted in acute tumor regression." (PMID 25538623, 2014). "FAP-α was also significantly increased in ER positive and ERβ positive tumours." (PMID 24885257, 2014). "It is possible that the contribution of FAP to immune suppression mighty vary depending on the tumor type." (PMID 23554941, 2013). "Importantly, the majority of FSP-1+ and FAP+ fibroblasts in the resulting tumour xenografts were shown to derive largely from GFP+ bone marrow cells including MSCs." (PMID 24216702, 2013). "We confirmed the induction of FAP expression within 5 days post B16 tumor implantation by RT-PCR." (PMID 24349329, 2013).